RNU6-193P (RNA, U6 small nuclear 193, pseudogene)
Gene: Small nuclear RNA gene on chromosome 10 (34,942,969 to 34,943,075, forward strand). Ensembl gene ENSG00000222909.
Homologues: Orthologues: chimpanzee U6 (99% identical), macaque U6 (94% identical). Paralogues in human: RNU6-1060P (77% identical), RNU6-15P (76% identical), RNU6-166P (76% identical), RNU6-17P (76% identical), RNU6-18P (76% identical), RNU6-19P (76% identical), RNU6-25P (76% identical), RNU6-29P (76% identical), RNU6-41P (76% identical), RNU6-492P (76% identical), RNU6-49P (76% identical), RNU6-820P (76% identical), and 1287 more.